CEP131 (centrosomal protein 131)
Description:
Component of centriolar satellites contributing to the building of a complex and dynamic network required to regulate cilia/flagellum formation. In proliferating cells, MIB1-mediated ubiquitination induces its sequestration within centriolar satellites, precluding untimely cilia formation initiation. In contrast, during normal and ultraviolet or heat shock cellular stress-induced ciliogenesis, its non-ubiquitinated form is rapidly displaced from centriolar satellites and recruited to centrosome/basal bodies in a microtubule- and p38 MAPK-dependent manner. Also acts as a negative regulator of BBSome ciliary trafficking. Plays a role in sperm flagellar formation; may be involved in the regulation of intraflagellar transport (IFT) and/or intramanchette (IMT) trafficking, which are important for axoneme extension and/or cargo delivery to the nascent sperm tail (By similarity). Required for optimal cell proliferation and cell cycle progression; may play a role in the regulation of genome stability in non-ciliogenic cells. Involved in centriole duplication (By similarity). Required for CEP152, WDR62 and CEP63 centrosomal localization and promotes the centrosomal localization of CDK2. Essential for maintaining proper centriolar satellite integrity.
Synonyms: AZI1; KIAA1118; AZ1; ZA1
Tractability: PROTAC: UniProt records ubiquitination sites on it; ubiquitination databases record sites on it; its protein half-life has been measured.
Gene: Protein-coding gene on chromosome 17 (81,189,592 to 81,223,014, reverse strand). Ensembl gene ENSG00000141577.
Subcellular location: Cytoplasm, cytoskeleton, microtubule organizing center, centrosome; Cytoplasm, cytoskeleton, microtubule organizing center, centrosome, centriolar satellite; Cytoplasm, cytoskeleton, microtubule organizing center, centrosome, centriole; Cytoplasm, cytoskeleton, cilium basal body; Cytoplasmic vesicle, secretory vesicle, acrosome
Subcellular location (Human Protein Atlas): Basal body; Centriolar satellite; Flagellar centriole; Cytokinetic bridge; Microtubules; Primary cilium
Pathways (Reactome):
Cell Cycle: AURKA Activation by TPX2; Loss of Nlp from mitotic centrosomes; Loss of proteins required for interphase microtubule organization from the centrosome; Recruitment of NuMA to mitotic centrosomes; Recruitment of mitotic centrosome proteins and complexes; Regulation of PLK1 Activity at G2/M Transition
Organelle biogenesis and maintenance: Anchoring of the basal body to the plasma membrane
Gene Ontology:
Molecular function: protein binding; protein homodimerization activity; protein-containing complex binding
Biological process: intraciliary transport involved in cilium assembly; positive regulation of cell population proliferation; positive regulation of intracellular protein transport; protein localization to centrosome; regulation of centrosome duplication; cilium assembly
Cellular component: centriolar satellite; centriole; centrosome; ciliary basal body; ciliary transition zone; microtubule cytoskeleton; cytosol; acrosomal vesicle
Genetic constraint (gnomAD): Loss-of-function variants: 96 observed, 110.28 expected, observed/expected ratio (o/e) 0.87, 90% interval 0.74 to 1.03. The upper end of that interval is the gene's LOEUF score, 1.03, which puts it in group 4 of 6, group 1 being the genes least tolerant of losing a copy. Missense variants: 1,444 observed, 1,355.1 expected, observed/expected ratio (o/e) 1.07, 90% interval 1.02 to 1.11. Synonymous variants: 641 observed, 559.27 expected, observed/expected ratio (o/e) 1.15, 90% interval 1.07 to 1.22.
Homologues: Orthologues: chimpanzee CEP131 (99% identical), macaque CEP131 (95% identical), guinea pig CEP131 (74% identical), mouse Cep131 (73% identical), rat Cep131 (70% identical), dog CEP131 (69% identical), pig CEP131 (60% identical), tropical clawed frog cep131 (54% identical), zebrafish cep131 (52% identical), Drosophila melanogaster dila (23% identical).
Diseases named in the same sentence as CEP131 in open-access papers:
CEP131 is named in the same sentence as 24 diseases in open-access papers, as found by Europe PMC text mining. Sharing a sentence is not in itself a finding about the gene and the disease. The quoted sentences say what the papers report.
breast carcinoma (9 papers, 2017 to 2025). "This has been observed in breast cancer, where the deubiquitinating enzyme USP9X, an integral component of the centrosome and required for centriole duplication, causes excessive levels of CEP131, thereby contributing to the pathogenesis of breast cancer." (PMID 38606093, 2024). "Different studies have reported that CEP131 functions as an oncogene, promoting carcinogenesis in breast cancer and tumour progression in colon cancer." (PMID 40320296, 2025). "This suggests that elevated Cep131 levels induced by loss of USP9X caused centrosome amplification and promoted breast cancer progression." (PMID 31358734, 2019). "Our experiments identify USP9X as an important regulator of centrosome biogenesis and uncover a critical role for USP9X/CEP131 in breast carcinogenesis, supporting the pursuit of USP9X/CEP131 as potential targets for breast cancer intervention." (PMID 28361952, 2017). "It will be also important to investigate the mechanisms underlying USP9X dysregulation in breast cancer and the role of the USP9X/CEP131 axis in the development/progression of breast cancer." (PMID 28361952, 2017). "Significantly, USP9X is overexpressed in breast carcinomas, and its level of expression is correlated with that of CEP131 and higher histologic grades of breast cancer." (PMID 28361952, 2017). "A previous study found that USP9X could promote the occurrence of breast cancer by regulating CEp131." (PMID 34856948, 2021). "As such, several lines of evidence show that increased expression of CEP131 is correlated with higher histologic grades of breast cancer and poor overall survival in hepatocellular carcinoma and advanced Tumor-Node-Metastasis stage of non-small cell lung cancer." (PMID 33014050, 2020). "In addition, a recent study showed that elevated Cep131 levels induced by loss of deubiquitinase USP9X promoted centrosome amplification and breast cancer development." (PMID 31358734, 2019). "Similarly, CEP131 is overexpressed in different types of human cancers, including hepatocellular cancer and breast cancer." (PMID 29899122, 2018). "Our observations support a model in which overexpression of USP9X in breast cancer results in elevated CEP131 protein, which, in turn, leads to centrosome amplification and genome instability, and eventually contributes to the development/progression of breast cancer." (PMID 28361952, 2017). "As an important DUB, USP9X regulates multi-types of cancer development, such as glioblastoma, lung cancer, colorectal cancer, and breast cancer, through mediating the stability of ALDH1A3, KDM4C, FBW7, CEP131, and Snail1." (PMID 40246814, 2025). "Additionally, we found genes highly expressed in breast cancer stroma in the Human Protein Atlas (EGR1, OSBPL8, FAM171A2, FGD6, and CEP131), or likely expressed in fibroblasts (MMP13), that are reported to play a role in breast cancer progression among the most important ones." (PMID 31505876, 2019).
ciliopathy (5 papers, 2018 to 2025). A genetic disorder of the cellular cilia or the cilia anchoring structures, the basal bodies, or of ciliary function. "This study shows that the Cep131-Cep162 module near the axoneme and the Cby-Fam92 module near the membrane work together to regulate the localization of the highly conserved ciliopathy protein Cep290 at the basal body to initiate ciliogenesis." (PMID 38442096, 2024). "In zebrafish, the homolog Cep131 regulates ciliogenesis and CEP131 knockout animals have phenotypes resembling human ciliopathies primarily characterized by renal and retinal defects." (PMID 35997111, 2022). "Our results reveal that the first step of ciliogenesis strictly depends on cooperative and retroactive interactions between Cep131-Cep162, Cby-Fam92 and Cep290, which may contribute to the complex pathogenesis of Cep290-related ciliopathies." (PMID 38442096, 2024). "While Cep131 and Cby have not yet been associated with ciliopathy, mutations in Cep162 and Fam92A have been reported to be linked to human cilia-related diseases." (PMID 38442096, 2024). "It is interesting to note that Drosophila and zebrafish lacking the relevant CEP131 orthologue show phenotypes reminiscent of human ciliopathies." (PMID 30266825, 2018). "Similarly, although tracheal multicilia also contain the CPF, neither the previous Azi1Gt/Gt nor our Cep131−/− mice displayed obvious ciliopathy-related symptoms in the respiratory system." (PMID 39165107, 2025). "Additionally, the transcriptional expression levels of several well-recognized cilia genes in the PBMCs, including CEP131, NEK8 and other cilia genes recorded in the SCGSv2 gold standard list, were substantially elevated in the genome-wide transcriptome profile of EVC ciliopathy patients." (PMID 37326025, 2023).
hepatocellular carcinoma (5 papers, 2018 to 2025). A malignant tumor that arises from hepatocytes. "Cep131, a regulator for centrosome duplication and genome stability, can function as an oncogene and promote cell proliferation and migration in hepatocellular carcinoma." (PMID 32245399, 2020). "Intriguingly, increased levels of CEP131 were recently reported in both hepatocellular carcinoma and breast carcinoma." (PMID 31519908, 2019). "Also, CEP131 overexpression has been reported as a predictor of poor prognosis in hepatocellular carcinoma and neuroblastoma." (PMID 40320296, 2025). "CEP131 overexpression promotes cell proliferation and migration in hepatocellular carcinoma through activating the phosphatidylinositol-3 kinase (PI3K)/AKT signaling pathway, therefore, CEP131 is an oncogene and a candidate prognostic marker in the disease." (PMID 33665015, 2021).
colon cancer (4 papers, 2019 to 2025). "The xenograft mouse model also showed that both centrosome amplification and colon cancer growth were significantly increased by Cep131 overexpression." (PMID 31358734, 2019). "Both database analyses demonstrated significantly increased expression of Cep131 in bladder and colon cancers." (PMID 31358734, 2019).
liver cancer (2 papers, 2022 to 2025). An epithelial or non-epithelial malignant neoplasm that arises from the liver. "Moreover, a high CEP131 or KDM3A level was associated with poor overall survival in liver cancer patients." (PMID 36008383, 2022). "Overexpression of either ARID3A or CEP131-induced KDM3A mRNA expression in liver cancer cells, and this induction was abolished by silencing either CEP131 or ARID3A." (PMID 36008383, 2022). "ARID3A can cooperate with CEP131 to transcriptionally activate KDM3A and promote expression of ES signature genes, suggesting that ARID3A and CEP131 are potential targets for the development of new anticancer therapeutics for liver cancer." (PMID 36008383, 2022). "Similar to the effects of silencing ARID3A expression, silencing the expression of CEP131 reduced the cell migration, invasion and tumoursphere formation capabilities, while overexpression of CEP131 enhanced these capabilities in liver cancer cells." (PMID 36008383, 2022). "Next, we investigated the biological function of CEP131 in liver cancer." (PMID 36008383, 2022). "Furthermore, we determined by Co-IP that endogenous ARID3A can interact with CEP131 in liver cancer cells." (PMID 36008383, 2022). "Furthermore, the mRNA level of KDM3A correlated significantly with that of CEP131 in liver cancer patients based on data from the TCGA-LIHC cohort." (PMID 36008383, 2022). "ARID3A interacts with CEP131 and co-occupies the KDM3A promoter region to activate KDM3A transcription, thereby modulating the expression of ES signature genes in liver cancer cells." (PMID 36008383, 2022). "ARID3A and CEP131 promote an ES cell gene signature through activation of KDM3A and contribute to the poor prognosis of liver cancer patients." (PMID 36008383, 2022). "In the present study, we demonstrated that ARID3A and CEP131 co-occupy the promoter region of KDM3A and contribute to its transcriptional activity, ultimately enhancing liver cancer cell oncogenic ability." (PMID 36008383, 2022). "Both the mRNA and protein levels of KDM3A were increased upon CEP131 overexpression, while knockdown of CEP131 reduced KDM3A expression, suggesting that KDM3A is also a downstream target of CEP131 in liver cancer cells." (PMID 36008383, 2022).
male infertility (2 papers, 2025). The inability of the male to effect fertilization of an ovum after a specified period of unprotected intercourse. "It was pointed out that in mice, male infertility is linked to the CEP131 loss that triggers defects in the manchette and flagella, indicating a possible link between CEP131 and the organization of cellular structures relying on LLPS." (PMID 40407495, 2025). "Several satellite genes have been associated with male infertility and sperm flagellum defects in humans and mice, including PCM1, CEP131, BBS4, OFD1, CEP290, CCDC13, etc.." (PMID 40801568, 2025). "Cep131-null mice exhibited male infertility and sperm flagella defects." (PMID 40801568, 2025). "In the Sdccag8mut/mut spermatid, lacking this region led to the instability of PCM1 and mislocalization of the satellite-associated proteins, CEP131, and BBS4, which could be attributed to observed male infertility, as CEP131 and BBS4 are essential for flagellum biogenesis and male fertility." (PMID 40801568, 2025).
neuroblastoma (2 papers, 2020 to 2025). Neuroblastoma (NB) is the most common solid, extracranial childhood tumor. "A mass spectrometry analysis of protein binding to MDM2 in the presence of CHK1i identified the centrosome-associated family protein 131 (CEP131), which was correlated with unfavorable prognosis of neuroblastoma patients." (PMID 33014050, 2020). "We revealed that MDM2 was associated with CEP131 protein degradation, whereas overexpression of CEP131 accelerated neuroblastoma cell growth and exhibited resistance to CHK1i-induced replication defects." (PMID 33014050, 2020). "In this study, we revealed that increased expression of CEP131 confer tolerability against replicative stress on cells and may be associated with proliferation in unfavorable neuroblastomas." (PMID 33014050, 2020). "We asked whether CEP131 expression could be associated with prognosis in patients with neuroblastoma." (PMID 33014050, 2020). "In the current study, we highlighted the possible role of CEP131 on replication stress (RS) in MYCN-amplified neuroblastoma NB-39-nu cell line." (PMID 33014050, 2020). "Then, we newly found that high expression of CEP131 was correlated with unfavorable prognosis of neuroblastoma patients and accelerated cell proliferation in neuroblastoma." (PMID 33014050, 2020). "Further studies about the precise mechanism by which CEP131 protects cells from RS could open the window to discover therapeutic strategy targeting to CEP131 and/or other centriolar satellites for effective neuroblastoma treatment." (PMID 33014050, 2020). "However, our present results suggested that unfavorable neuroblastomas might rely, in part, on CEP131 function to maintain their genome integrity against oncogene-induced RS in a hyperproliferative state." (PMID 33014050, 2020). "Collectively, CEP131 may have prognostic potential for unfavorable neuroblastoma patients and be negatively regulated by MDM2 in neuroblastoma." (PMID 33014050, 2020).
Bardet-Biedl syndrome (1 paper, 2009). A ciliopathy with multisystem involvement. "The resemblance of both cep70 and cep131 morphants to those of zebrafish IFT57 and IFT88 makes the two proteins candidates for genes mutated in inherited human diseases similar to Bardet-Biedl syndrome in which cilia in a number of tissues are affected." (PMID 19254375, 2009).
breast tumours (1 paper, 2017). "Moreover, we demonstrated that overexpression of CEP131 in USP9X-deficient tumours could restore the growth of breast tumours." (PMID 28361952, 2017).
Hydrocephalus (1 paper, 2025). Hydrocephalus is an active distension of the ventricular system of the brain resulting from inadequate passage of CSF from its point of production within the cerebral ventricles to its point of absorption into the systemic circulation. "Future studies are still required to comprehensively understand pathological mechanisms underlying the late-onset hydrocephalus of Cep131−/− mice." (PMID 39165107, 2025). "Although Cep131 deficiency seriously paralyzes multicilia in 15.4% of ependymal MCCs in 8-month-old mice, we only observed hydrocephalus in a portion of Cep131-deficient mice that were older than 18 months." (PMID 39165107, 2025). "Consequently, cilia became prone to ultrastructural abnormality and paralysis, and Cep131-deficient mice were susceptible to late-onset hydrocephalus." (PMID 39165107, 2025). "As defects in the CA of ependymal multicilia probably lead to hydrocephaly in mice, we examined serial brain slices from Cep131−/− mice of different ages." (PMID 39165107, 2025).
oropharyngeal squamous cell carcinoma (1 paper, 2021). "Here, we observed that USP9X-depleted HeLa and UMSCC74A oropharyngeal squamous cell carcinoma cells have reduced levels of CEP55 and CEP131." (PMID 34277417, 2021).
osteosarcoma (1 paper, 2015). A usually aggressive malignant bone-forming mesenchymal neoplasm, predominantly affecting adolescents and young adults. "In agreement with our previous findings, ultraviolet irradiation of human U2OS osteosarcoma cells led to a quantitative loss of CEP131, PCM1 and SSX2IP from CS in a p38-dependent manner." (PMID 26616734, 2015).
pulmonary fibrosis (1 paper, 2023). Chronic progressive interstitial lung disorder characterized by the replacement of the lung tissue by connective tissue, leading to progressive dyspnea, respiratory failure, or right heart failure. "Deficiency in O‐GlcNAcylation disperses PCM1 and CEP131, impairs the connections between microtubules and the centrosome, and disturbs cell polarity, which could be an underlying mechanism of pulmonary fibrosis." (PMID 37963851, 2023).
teratozoospermia (1 paper, 2025). "Therefore, Cep131 deficiency severely impairs the morphogenesis of spermatids and results in teratozoospermia in male mice." (PMID 39165107, 2025).